TFR2 (transferrin receptor 2)
Description:
Mediates cellular uptake of transferrin-bound iron in a non-iron dependent manner. May be involved in iron metabolism, hepatocyte function and erythrocyte differentiation.
Synonyms: HFE3; TFRC2
Tractability: Antibody: a drug acting on it is in phase 1 trials; its Gene Ontology location is reachable by antibodies, with high confidence; UniProt places it where antibodies can reach, with medium confidence; UniProt predicts a signal peptide or a membrane-spanning region. PROTAC: ubiquitination databases record sites on it; its protein half-life has been measured. Other modalities: a drug acting on it is in phase 2 or 3 trials.
Gene: Protein-coding gene on chromosome 7 (100,620,416 to 100,642,779, reverse strand). Ensembl gene ENSG00000106327.
Subcellular location: Cell membrane; Cytoplasm (Isoform Beta)
Subcellular location (Human Protein Atlas): Golgi apparatus
Pathways (Reactome):
Transport of small molecules: Transferrin endocytosis and recycling
Gene Ontology:
Molecular function: co-receptor binding; protein binding; transferrin receptor activity
Biological process: cellular response to iron ion; endocytic iron import into cell; intracellular iron ion homeostasis; multicellular organismal-level iron ion homeostasis; positive regulation of endocytosis; positive regulation of peptide hormone secretion; positive regulation of protein maturation; positive regulation of transcription by RNA polymerase II; receptor-mediated endocytosis; response to iron ion; transferrin transport; iron ion transport
Cellular component: cytoplasmic vesicle; external side of plasma membrane; HFE-transferrin receptor complex; plasma membrane; cytoplasm
Genetic constraint (gnomAD): Loss-of-function variants: 64 observed, 86.91 expected, observed/expected ratio (o/e) 0.74, 90% interval 0.6 to 0.91. The upper end of that interval is the gene's LOEUF score, 0.91, which puts it in group 3 of 6, group 1 being the genes least tolerant of losing a copy. Missense variants: 950 observed, 1,065.8 expected, observed/expected ratio (o/e) 0.89, 90% interval 0.84 to 0.94. Synonymous variants: 454 observed, 443.78 expected, observed/expected ratio (o/e) 1.02, 90% interval 0.95 to 1.11.
Gene-disease validity (ClinGen):
ClinGen rates the evidence that TFR2 causes each of these diseases.
hemochromatosis type 3 (autosomal recessive): Definitive. Type 3 hemochromatosis is a form of rare hereditary hemochromatosis (HH), a group of diseases characterized by excessive tissue iron deposition of genetic origin.
Homologues: Orthologues: chimpanzee TFR2 (99% identical), macaque TFR2 (98% identical), dog TFR2 (88% identical), pig TFR2 (88% identical), mouse Tfr2 (85% identical), rat Tfr2 (84% identical), guinea pig TFR2 (83% identical), zebrafish tfr2 (47% identical), tropical clawed frog tfr2 (43% identical). Paralogues in human: TFRC (41% identical), NAALADL1 (24% identical), FOLH1 (24% identical), NAALAD2 (23% identical), NAALADL2 (20% identical).
Diseases named in the same sentence as TFR2 in open-access papers:
TFR2 is named in the same sentence as 69 diseases in open-access papers, as found by Europe PMC text mining. Sharing a sentence is not in itself a finding about the gene and the disease. The quoted sentences say what the papers report.
hemochromatosis (47 papers, 2005 to 2025). A disorder of iron metabolism characterized by a triad of HEMOSIDEROSIS; LIVER CIRRHOSIS; and DIABETES MELLITUS. "Mammalian systemic iron homeostasis is mainly modulated by hepcidin, the synthesis of which is regulated by a number of proteins, including the hemochromatosis-associated proteins Hfe and Transferrin Receptor 2 (TfR2)." (PMID 39273097, 2024). "Hepc transcription is controlled by numerous upstream regulators, including hemochromatosis-associated proteins such as Hfe and TfR2." (PMID 39273097, 2024). "Mutations in human HFE and TFR2 genes cause Hemochromatosis type 1 and 3, respectively, a genetic heterogeneous disease that results in body iron accumulation due to abnormally low Hepc production." (PMID 39273097, 2024). "Here, we first reported a Chinese pedigree of TFR2-related hemochromatosis with a novel compound heterozygous mutation c.1288G > A (p.G430R)/c.960T > A (p.Y320X)." (PMID 35464850, 2022). "HFE and TfR2 (transferrin receptor 2) are presumably auxiliary factors, since their inactivation is associated with milder hemochromatosis." (PMID 33096618, 2020). "There is a reported case of juvenile hemochromatosis resulting from TfR2 mutation and serum hepcidin levels are lower in TfR2 HH patients." (PMID 24639653, 2014). "The type of iron overload caused by mutations in TFR2 differs from the classic type 1 HFE-hemochromatosis, because of an earlier onset and more severe presentation." (PMID 24847265, 2014). "These molecules include HFE (HLA2-linked hemochromatosis gene), transferrin receptor 2 (TfR2), hemojuvelin (HJV) and bone morphogenetic protein (BMP)." (PMID 24731443, 2014). "If iron overload were indeed present it would be worthwhile testing for other hemochromatosis associated mutations, namely transferrin receptor 2 (tfr2) and ferroportin (fpn)." (PMID 22550530, 2012). "Hepcidin levels are significantly decreased in hemochromatosis associated with TFR2, FPN1, and HJV mutations." (PMID 16042809, 2005). "Although rare, mutations in TFR-2 may be the leading cause of hemochromatosis in the Asia Pacific region where the I238M variant of TFR2 (previously reported as a polymorphism) has an allele frequency of 7%." (PMID 37067673, 2023). "In addition, it was recently reported that TfR2 facilitates iron transport from lysosomes to mitochondria in erythroblasts and dopaminergic neurons, and defects in the TfR2 can cause systemic iron overload, hemochromatosis." (PMID 33334049, 2020). "TFR2 is a hepatocyte membrane protein whose mutations can lead to hemochromatosis." (PMID 30958854, 2019). "Hepcidin deficiency is a result of autosomal recessive mutations in the hepcidin gene or genes encoding hepcidin regulators, the hemochromatosis gene (HFE, most commonly mutated in hereditary hemochromatosis in Caucasians populations), transferrin receptor 2 (TfR2), or hemojuvelin." (PMID 30984307, 2019). "Mutations in the High Iron Fe (HFE) genes (C282Y or H63D), less frequent mutations in the genes coding for hepcidin, ferroportin, transferrin receptor 2 or hemojuvelin (HFE2) are causes of hemochromatosis, which are characterized by the increased absorption of iron." (PMID 29113123, 2017). "A less severe form of hemochromatosis, associated with a less dramatic decrease in hepcidin expression, is caused by disrupted synthesis of two other membrane proteins: transferrin receptor 2 (Tfr2) and the Hfe protein." (PMID 22629388, 2012). "It elucidates diverse inheritance patterns and clinical manifestations by exploring mutations in critical genes such as HFE (hemochromatosis), HJV (hemojuvelin), HAMP (hepcidin antimicrobial peptide), TfR2 (transferrin receptor 2), and FP (ferroportin)." (PMID 39114232, 2024). "Mutations in five key genes - HFE (hemochromatosis), HJV (hemojuvelin), HAMP (hepcidin antimicrobial peptide), TfR2 (transferrin receptor 2), and FP (ferroportin) - are responsible for HH." (PMID 39114232, 2024).
hemochromatosis (continued). "This study reports the systemic and local effects of two major hemochromatosis proteins on iron metabolism in a new double knockout mouse model (Hfe/TfR2 KO, DKO), in which the Hfe and TfR2 genes were selectively silenced in macrophages." (PMID 39273097, 2024). "The hereditary hemochromatosis-associated membrane proteins HFE, TFR2, and HJV are required for adequate hepatic expression of the iron hormone hepcidin." (PMID 35163229, 2022). "On the other hand, four types (types 1, 2, 3, and 4) of hemochromatosis have been genetically classified on the basis of mutations in five genes (HFE, human antimicrobial peptide [HAMP], hemojuvelin [HJV], transferrin receptor 2 [TFR2], and SLC40A1)." (PMID 33673803, 2021). "Deletion of Tfr2 in mice leads to an acute iron overload called hemochromatosis mimicking the human disease hereditary hemochromatosis type 3 due to TFR2 mutations." (PMID 33352721, 2020). "TfR2 hemochromatosis (type 3; OMIM #604250) is linked to inactivation of the TFR2 gene on chromosome 7q22, which encodes transferrin receptor 2 (TfR2)." (PMID 30420953, 2018). "Mutations in the genes transferrin receptor 2 (TfR2), ferroportin, and hemojuvelin (HJV) can also cause hemochromatosis." (PMID 30360383, 2018). "Holo-Tf displaces the interaction of hereditary hemochromatosis protein (HFE)-TfR1 and stabilizes the association of HFE-TfR2 with membrane-anchored hemojuvelin (mHJV), forming a complex of HFE/TfR2/HJV which is dispensable for hepcidin transcription." (PMID 30150549, 2018). "This occurs also in humans: patients with mutation in TFR2 and HFE were reported to develop a severe form of juvenile-like hemochromatosis." (PMID 24847265, 2014). "Liver TFR2 is considered a sensor of diferric transferrin, possibly in a complex with hemochromatosis protein." (PMID 24847265, 2014). "Accordingly, the combined defect in HFE and TfR2 in man has been shown to lead to more severe iron loading and a juvenile form of hemochromatosis, suggesting that these two genes have a least some hepcidin regulatory functions that do not overlap." (PMID 21408141, 2011). "Liver hepcidin-1 mRNA levels as well as serum Hep-1 levels were decreased in all three hemochromatosis models and lowest in the double affected Hfe/TfR2 y245x mice." (PMID 21408141, 2011). "Mutations within several genes have been associated with HH, these include hemochromatosis (HFE), hemojuvelin (HJV), transferrin receptor 2 (TfR2), and hepcidin (HAMP)." (PMID 20670400, 2010). "The hemochromatosis protein HFE, transferrin receptor 2 (TfR2) and the membrane isoform of hemojuvelin (mHJV) are all positive modulators of hepcidin transcription and when defective, lead to hemochromatosis (HH) in humans." (PMID 20827391, 2010). "Additionally, hepcidin is highly dependent on transferrin receptor 2 (TfR2) and hereditary hemochromatosis protein (HFE), a human homeostatic iron regulator protein encoded by the HFE gene." (PMID 35052868, 2022). "Adipocytes express common regulators of iron homeostasis including iron-regulatory proteins (e.g. ferritin and hepcidin), as well as iron-related proteins with restricted tissue expression (e.g. TfR2-Transferrin Receptor 2, HFE-encoding Human hemochromatosis protein, and HAMP-hepcidin)." (PMID 28651003, 2017). "In addition to functional differences in Tf handling, TfR1 and TfR2 appear to interact with the original hereditary hemochromatosis protein (HFE) through alternate domains." (PMID 24639653, 2014). "Patients affected by hemochromatosis have a defective synthesis of hepcidin that is absent in JH, reduced in type 3 HH due to TFR2 mutation or inadequate to the amount of iron overload in classical HH38." (PMID 21415988, 2009). "Indeed, double heterozygotes for HFE and TFR2 mutations develop hemochromatosis 43, whereas this does not occur in carriers of single allelic mutations in both HFE and HJV44,45, suggesting they behave to different pathways of hepcidin regulation." (PMID 21415988, 2009).
hemochromatosis (continued). "This protein is found on the membrane of hepatocyte cells and is a component of the iron sensing complex together with the hemochromatosis gene (HFE) and transferrin receptor 2 (TFR2)." (PMID 36895478, 2023). "Neither novel HFE alleles nor deleterious alleles in TFR2, HAMP, and SCL40A1 were detected in referred hemochromatosis patients with p.H63D/p.H63D." (PMID 35895739, 2022). "As hemochromatosis can also be caused by other mutation in the HFE gene or so called non-HFE hemochromatosis genes (HJV, HAMP, TFR2), homozygosity for p.Cys282Tyr is neither sufficient nor necessary for the diagnosis hemochromatosis." (PMID 30514216, 2018). "However, Tfr2 null mice as well as TFR2 hemochromatosis patients do not show defective erythropoiesis and tolerate repeated phlebotomy." (PMID 24847265, 2014). "Moreover, although TFR2 is required for efficient erythropoiesis, Tfr2 null mice as well as TFR2 hemochromatosis patients do not show defective erythropoiesis and patients tolerate repeated courses of phlebotomy without developing anemia." (PMID 24847265, 2014).
iron overload (37 papers, 2005 to 2025). "We had access to microarray data from a published cohort of transferrin receptor 2 (TFR2)-mutant mice susceptible to spontaneous iron overload." (PMID 34480898, 2021). "Mutations of HFE, hemojuvenil, hepcidin, transferrin receptor 2 (TfR2), Ireg1, transferrin, ceruloplasmin and ferritin all lead to some form of iron overload." (PMID 27363994, 2016). "The Transferrin Receptor 2 (Tfr2) modulates systemic iron metabolism through the regulation of iron regulator Hepcidin (Hepc) and Tfr2 inactivation causes systemic iron overload." (PMID 27477597, 2016). "TFR2 gene is mutated in type 3 hemochromatosis, a disorder characterized by iron overload and inability to upregulate hepcidin in response to iron." (PMID 24847265, 2014). "In humans inactivating mutations of TFR2 lead to hemochromatosis type 3, a rare recessive disorder characterized by iron overload, low hepcidin levels and inability to properly regulate hepcidin after an oral iron challenge." (PMID 24847265, 2014). "Mutations in either TfR2 or HFE can result in iron overload, which is characterised by low hepcidin expression." (PMID 21978626, 2011). "An increasing number of mutations in other genes (ferroportin, transferrin receptor 2 and aceruloplasminemia) have been identified as causing iron overload." (PMID 16878186, 2006). "An associated hereditary iron overload such as transferrin receptor 2 haemochromatosis in this Italian patient cannot be ruled out." (PMID 15871739, 2005). "Moreover, the SLC40A1 gene may interact with the HFE, TFR2 genes, causing hyperferritinemia and an iron overload phenotype." (PMID 25162662, 2014). "Variants at DUOX2, F5, SLC11A2 and TMPRSS6 associate with iron deficiency anemia, while variants at TF, HFE, TFR2 and TMPRSS6 associate with iron overload." (PMID 33536631, 2021). "We found that TfR2 deletion can provide neuroprotection against dopaminergic degeneration, and against PD- and aging-related iron overload." (PMID 33323945, 2021). "In terms of genetics, different types of hereditary hemochromatosis are caused by mutations in the HFE, hepcidin (HAMP), hemojuvelin (HJV), ferroportin (SLC40)A1, and transferrin receptor 2 (TfR2) genes that correspond to genetic disorders of iron overload." (PMID 32635533, 2020). "Murine models of iron overload, that include KO (Knock-out) mice (Hfe-KO, Hjv-KO, Tfr2-KO) and iron dextran intraperitoneal administration, were used to better investigate the effects that iron overload has on organs and cells." (PMID 32079304, 2020). "In fact, Tfr2 KO mice have less severe iron overload, slightly higher hemoglobin (Hb) levels, and moderate macrocytosis than Tfr2 LCKO." (PMID 30360575, 2018). "TFR2 genotyping should be considered in adult but also in pediatric cases with early-onset of iron overload." (PMID 26029709, 2015). "Tfr2-/- mice have slightly less severe iron overload than liver-specific (Tfr2LCKO) knock-out, slightly higher Hb levels and moderate macrocytosis." (PMID 24847265, 2014). "In mice, deletion of the iron regulatory protein hepcidin and genes that regulate iron biology, such as Hfe, transferrin receptor 2 (Tfr2), hemojuvelin (Hjv) and ferroportin (Fpn) cause iron overload but not organ disease." (PMID 40149659, 2025). "It has been reported that a high dose of curcumin can upregulate hepcidin and its regulators, such as bone morphogenic protein (BMP-6) Sekelsky Mothers Against DPP (SMAD) and transferrin receptor 2 (TfR2), in a mouse model of aplastic anemia with iron overload." (PMID 34070628, 2021). "In this study, we examined the Tfr2 KO mouse model of iron overload to determine whether oral administration of rutin can be used to rescue mice from iron overload typical of that seen in Type 3 HH patients." (PMID 34156073, 2021). "The severity of iron overload increases in the order from HFE-/- to TFR2-/- to HJV-/- or HAMP-/-." (PMID 30608934, 2019).
iron overload (continued). "Inactivating mutations of TFR2 gene (OMIM: 604720) lead to type 3 hereditary hemochromatosis (TFR2-HHC or HFE3), a rare recessive disorder characterized by increased transferrin saturation and serum ferritin concentration and iron overload." (PMID 30360575, 2018). "Transferrin receptor 2 (Tfr2) is one of the hepcidin regulators, and mutations in TFR2 gene are responsible for type 3 hereditary hemochromatosis (HFE3), a genetically heterogeneous disease characterized by systemic iron overload." (PMID 30360575, 2018). "Moreover, there are other point mutations including H63D and non-HFE gene mutations such as hemojuvelin (HJV), hepcidin (HAMP), transferrin receptor 2 (TfR2), and ferroportin (SLC40A1) that are shown to cause milder degree of iron overload." (PMID 24024049, 2013). "Although a lot of genes are involved in these pathways, we chose to measure FPN1, TfR1, TfR2 and HJV mRNA expression because mutations in Tfr2, HJV, and FPN1 prevent appropriate hepcidin response to iron, allowing increased absorption of dietary iron, and eventually iron overload." (PMID 29065180, 2017). "Other mutations, such as H63D in HFE or mutations in non-HFE genes like HAMP, HJV, TFR2, and SLC40A1 (FPN1), also contribute to iron overload but tend to have a variable clinical impact." (PMID 39323676, 2024). "We used the Tfr2 KI animals (α+β0), in which circulating iron levels are normal, and the Tfr2 KO mice (α0β0), that have severe iron overload in addition to increased serum ferritin and transferrin saturation." (PMID 28540293, 2017). "It provides new data on the induction of splenic ERFE and TFR2 by EPO, suggesting that the induced levels of these proteins are not further posttranscriptionally regulated by iron overload, but that the EPO-induced splenic TFR2 protein levels are decreased by iron deficiency." (PMID 30958854, 2019).